PRL (prolactin)
Diseases named in the same sentence as PRL in open-access papers (continued):
Sharing a sentence is not in itself a finding about the gene and the disease.
breast cancer (continued). "Our previous results emphasized PRL/PRLR pathway as a promoter of differentiation in breast cancer cells driving favorable patient outcomes." (PMID 40157909, 2025). "High circulating levels of PRL increase the synthesis and expression of PLRr in malignant mammary tissue, increasing DNA synthesis in breast cancer cells." (PMID 40160874, 2025). "STAT5 can be activated by several cytokines or growth factors in breast cancer, including prolactin (PRL), growth hormone, epidermal growth factor (EGF), and insulin-like growth factor (IGF)." (PMID 40507264, 2025). "Prolactin-induced STAT5 can also repress expression of B-cell lymphoma 6 (BCL6) in breast cancer cells through direct binding to the gene." (PMID 40507264, 2025). "Mechanistically, PRL treatment of mammary and breast cancer cells resulted in Hippo pathway activation, thereby induced nuclear exclusion of the oncoprotein YAP." (PMID 40157909, 2025). "These analyses emphasize CCN2 gene as part of the Hippo pathway and implicate Hippo pathway in regulating PRL differentiation effects in breast cancer." (PMID 40157909, 2025). "To validate the implication of these bioinformatics results, we evaluated PRL’s role in activating the Hippo pathway in the HR+ breast cancer cells MCF7." (PMID 40157909, 2025). "To expand our understanding of the differentiation role of PRL in breast cancer in relation to the A/B polarity players, we next employed bioinformatics analysis." (PMID 40157909, 2025). "For example, prolactin stimulates ER expression and works in concert with progesterone receptor to promote autocrine secretion-mediated mammary epithelial cell and breast cancer proliferation." (PMID 38553763, 2024). "Results of retrospective studies examining the relationship between prolactin increasing antipsychotics and incident breast cancer have been inconsistent." (PMID 38595824, 2024). "Long-term use of prolactin-increasing antipsychotics has been associated with infertility, decreased bone mineral density, and fragility fractures in people with severe mental illness, and may also contribute to an increased likelihood of breast cancer in women." (PMID 38687213, 2024). "Previously, we have shown that pTyr-PAK1 plays a significant role in PRL-induced breast cancer cell motility and metastasis in micein vivoas only cells overexpressing PAK1, but not PAK1 Y3F, were able to migrate from the primary tumor to the lungs." (PMID 38660565, 2024). "Taken together, the observed accumulation of iron in mammary cancer cells by prolactin stimulation was at least partly mediated through the upregulation of CD44, which transported hyaluronate-Fe." (PMID 39201626, 2024). "The same upregulation of CD44 by prolactin stimulation was also reproduced with another mouse mammary cancer cell line, Py230." (PMID 39201626, 2024). "Hormones estrogen and prolactin exert independent effects on breast cancer while their crosstalk synergistically enhance breast cancer cell proliferation." (PMID 38933712, 2024). "Prolactin (PRL) has a high specificity toward breast cancer (BC), making it a valuable marker in both diagnosis and prognosis." (PMID 38756317, 2024). "Both PAK1 activities are important for PRL-dependent breast cancer cell adhesion, motility, and invasion." (PMID 38660565, 2024). "In contrast to the results observed in breast cancer cells, prolactin stimulation in the normal mouse mammary epithelial cell line HC11 led to a significant downregulation of CD44." (PMID 39201626, 2024). "An observational study revealed a positive correlation between prolactin levels and triglycerides in breast cancer patients." (PMID 38399363, 2024). "Since we have previously shown that PAK1, in response to PRL, increases the breast cancer cells migration and invasionin vitro; reviewed in and) as well as metastasisin vivo, we focused the present study on the role of pTyr-PAK1 in regulation of EMT." (PMID 38660565, 2024).
breast cancer (continued). "In KEGG pathway analysis, we identified 24 enriched pathways with a q-value < 0.1, including endocrine resistance, estrogen signaling pathway, prolactin signaling pathway, and breast cancer." (PMID 39452108, 2024). "This study assessed the association between use of high prolactin increasing antipsychotics (HPD) and the incidence of breast cancer using best practices in pharmacoepidemiology." (PMID 38595824, 2024). "The available research predominantly pertains to the role of GABA in breast cancer metastasis or to the regulation of prolactin secretion by GABA in the hypothalamus and pituitary gland." (PMID 38535871, 2024). "In the present study, we show distinct responses in iron transport due to prolactin treatment in two types of cells: mammary cancer cells and immune macrophages." (PMID 39201626, 2024). "There is mounting evidence that peptide hormone/cytokine prolactin (PRL) plays a significant role in breast cancer." (PMID 38660565, 2024). "pTyr- PAK1 also stimulated invasion of breast cancer cells in response to PRL and three-dimensional collagen IV(Rider, Oladimeji, & Diakonova, 2013)." (PMID 38660565, 2024). "In spite of this, AEA has been previously reported to mediate CB1R-dependent downregulation of PRLR in breast cancer cells, thus rendering them insensitive to the mitogenic action of PRL." (PMID 38184644, 2024). "More cases (n = 300, 18.3%) had been exposed to prolactin-increasing antipsychotics for 1–<5 years than controls (n = 1384, 16.9%); compared with minimal exposure (< 1 year), the aOR for breast cancer was 1.20 (95% CI = 1.03–1.41)." (PMID 38687213, 2024). "When stimulated by prolactin, breast cancer cells increase CD44, a surface receptor mediating the endocytosis of hyaluronate-bound iron, resulting in the accumulation of iron in cancer cells." (PMID 39201626, 2024). "All SSRIs increase the basal level of prolactin in the body to a greater or lesser extent, and prolactin concentration is closely related to the proliferation and differentiation of breast cancer cells." (PMID 37540479, 2024). "The logistic and LASSO regression models included three predictive factors, namely, the duration of breast cancer, hip fracture index, and prolactin." (PMID 37182163, 2023). "It is currently known that PRL-PRLR/JAK2-STAT5 is the principal signaling loop mediating the pathological functions of PRL in breast cancer." (PMID 37834225, 2023). "We examined the potential etiologic role of prolactin in the development of breast cancer within a large case–control study nested in a prospective cohort of women with pre-diagnosis blood and breast tumor tissue." (PMID 36882838, 2023). "This is likely due to the propensity of breast cancer to metastasize to the bone as well as possibly the prolactin-rich environment of the pituitary." (PMID 37899389, 2023). "According to a meta-analysis, elevated PRL levels were positively correlated with the development of breast cancer." (PMID 37900385, 2023). "It is found that prolactin-directed mammary epithelial cell differentiation program related to STAT5A offer a good prognosis in human breast cancer." (PMID 38124049, 2023). "The JAK2-STAT3 and JAK2-STAT5 pathways have been demonstrated to be constitutively active in luminal breast cancer via the stimulation of IL-6 and PRL, respectively." (PMID 37834225, 2023). "The three variables selected were the duration of breast cancer, hip fracture index, and prolactin, which were consistent with the results of the logistic model." (PMID 37182163, 2023). "MMP1-3 secretion in breast cancer cells is stimulated by the activation of the PRL/PAK1 signaling pathway via COL4A1." (PMID 38004422, 2023). "Six significant risk factors were identified by univariate analysis, including duration of breast cancer, duration of aromatase inhibitor therapy, major osteoporotic fracture index, hip fracture index, PRL, and OC." (PMID 37182163, 2023).
breast cancer (continued). "Assuming that the probability of AIBL in patients with hormone receptor-positive breast cancer treated with aromatase inhibitors is P, Logit(P) = −1.272 + 0.079 * (duration of breast cancer) + 3.673 * (hip fracture index) − 0.007 * (PRL)." (PMID 37182163, 2023). "Duration of breast cancer, duration of aromatase inhibitor therapy, hip fracture index, major osteoporotic fracture index, prolactin (PRL), and osteocalcin (OC) were found to be independent risk factors for AIBL (p < 0.05)." (PMID 37182163, 2023). "One way of protecting against breast cancer is to prescribe prolactin-sparing antipsychotics to women with schizophrenia while keeping doses as low as possible." (PMID 37759839, 2023). "Multivariate logistic regression analysis revealed that the three relevant variables included in the logistic model were the duration of breast cancer, hip fracture index, and PRL." (PMID 37182163, 2023). "Hip fracture index and prolactin were found to be the two most important factors, accounting for more than half of the proportion, followed by the duration of breast cancer and osteocalcin level, which accounted for one-third." (PMID 37182163, 2023). "A strong correlation between breast cancer with increased PRL and PRLR has been reported in several studies." (PMID 36187116, 2022). "Like PRL, it can be produced locally by breast cancer cells, and hGH and PRL receptors can heterodimerize." (PMID 35784527, 2022). "We first measured the serum levels of six hormones (LH, E2, T, P, FSH, and PRL) in postmenopausal patients with breast cancer by CLIA." (PMID 35712498, 2022). "This study measured serum levels of reproductive hormones, namely, luteinizing hormone (LH), E2, P, testosterone (T), follicle-stimulating hormone (FSH), and prolactin (PRL) in postmenopausal patients with breast cancer." (PMID 35712498, 2022). "Although PRLR is highly expressed by many tumors across breast cancer subtypes, data from small clinical trials inhibiting PRL action are difficult to interpret, and studies of xenografts, particularly of breast cancer cell lines, are conflicting." (PMID 35784527, 2022). "NEK3 kinase has been shown to regulates PRL-mediated cytoskeletal reorganization and motility of breast cancer cells." (PMID 36187116, 2022). "It was further shown to inhibit prolactin-induced osteoclast differentiation and bone lysis in breast cancer cells." (PMID 36714582, 2022). "In premenopausal women with breast cancer, there are higher-than-average levels of serum PRL together with elevated PRLR expression." (PMID 36187116, 2022). "The emerging data support complex actions of PRL in breast cancer biology, resembling the major recognized hormonal actor in breast cancer, estrogen." (PMID 35784527, 2022). "We have demonstrated that ECM structure can strongly influence the spectrum of PRL signals and PRL-estrogen crosstalk in ER+ breast cancer cells, and reciprocally, that these hormones can modify ECM structure." (PMID 35784527, 2022). "Both estrogens and prolactin have been shown to increase the incidence of spontaneous and chemically induced mammary tumors in rodents." (PMID 36425551, 2022). "Several studies using breast cancer cells have shown that PRL activates unliganded ERα through phosphorylation at the Ser118 and Ser167 residues." (PMID 36187116, 2022). "In breast cancer cell lines representing different cancer subtypes, PRL promoted to resistance to chemotherapies, including doxorubicin, paclitaxel, and cisplatin." (PMID 35784527, 2022). "An autocrine/paracrine loop increases PRLR mRNA expression via its ligand PRL in breast cancer cells." (PMID 36187116, 2022). "In another small Phase II trial (20 breast cancer patients), the dopamine D2 receptor agonist, cabergoline, was used to inhibit secretion of pituitary PRL; two of these patients experienced extended disease control." (PMID 35784527, 2022).
breast cancer (continued). "This is illustrated in ER+ cancers, the breast cancer subtype in which PRL actions are currently best understood." (PMID 35784527, 2022). "In breast cancer, PRL-mediated JAK/STAT signaling contributes to endocrine therapy resistance in conjunction with elevated HER2, by activating oncogenic factors such as MYC, FOS, and JUN." (PMID 36714582, 2022). "In another study, SNPs were found in PRL, and PRLR genes were associated with breast cancer metastasis in Taiwanese women." (PMID 36187116, 2022). "PRLR is highly expressed in many breast cancers across all different subtypes, and epidemiologic analyses and experimental studies are revealing that PRL can elicit both pro-differentiation and pro-aggression outcomes." (PMID 35784527, 2022). "Estradiol induces transcriptional activation/expression of the PRLR gene, and subsequent studies revealed the essential role of autocrine PRL released by breast cancer cells and CDK7 in estradiol-induced PRLR promoter activation and upregulation." (PMID 36187116, 2022). "In contrast to the strong epidemiologic data supporting a role for PRL in development of breast cancer, particularly of ER+ tumors, its role in established cancers continues to be actively debated." (PMID 35784527, 2022). "In another study, G129R-hPRL was fused to endostatin, and was shown to inhibit PRL-induced signaling in T47D breast cancer cells, while further suppressing HUVEC cell proliferation, tube formation, and tumor formation of mouse 4T1 cells in vivo." (PMID 36714582, 2022). "Most studies have examined the outcome of the sum of all PRL-initiated signals in different breast cancer settings." (PMID 35784527, 2022). "Data were unavailable to confirm the effect of antipsychotic treatment termination or PRL lowering on the prevalence of breast cancer, which requires more studies." (PMID 36591471, 2022). "As well, PRL was recently found to sensitize ER+ breast cancer cells to tamoxifen in a xenograft mouse model expressing hPRL gene." (PMID 36157462, 2022). "This explains why dopamine agonists, including bromocriptine, are ineffective in patients with PRL-dependent breast cancer." (PMID 36591471, 2022). "Altogether, these results implicate that loss of PRL/PRLR expression contributes to the initiation and progression of breast cancer and argues against a role for PRL/PRLR in promoting breast tumorigenesis." (PMID 36157462, 2022). "PRL plays a crucial role in mammary gland development and in the etiology and progression of breast cancer." (PMID 36187116, 2022). "Multiple epidemiologic studies have examined the relationship between levels of circulating PRL and development of breast cancer [meta-analysis and review,]." (PMID 35784527, 2022). "In the European Prospective Investigation into Cancer and Nutrition cohort, postmenopausal women with higher circulating PRL who had used combined estrogen/progestin MHT had the most significant increase in incidence of ER+ breast cancer." (PMID 35784527, 2022). "Assessing the expression levels of PRLR in breast cancer cases is vital to further define the role of PRL in breast cancer." (PMID 36157462, 2022). "The NSG-Pro mouse is a powerful tool to interrogate the actions of PRL in diverse clinical breast cancers in a dynamic in vivo environment." (PMID 35784527, 2022). "Prolactin also partially restored FA oxidation when CPTIA and AMPK were knocked down, demonstrating the crucial role prolactin plays in promoting FA oxidation in breast cancer." (PMID 35448537, 2022). "Studies are needed to accurately evaluate the effects of autocrine/paracrine PRL on breast cancer and antipsychotic drug-induced breast cancer." (PMID 36591471, 2022). "They underscore the need for additional study of PRL in diverse clinical breast cancers, changes with disease progression and therapeutic pressure, and influences of the metastatic sites." (PMID 35784527, 2022).
breast cancer (continued). "High doses of prolactin have been proven to have an antiapoptotic effect in certain types of tumors, e.g., breast cancer or myeloma, and support their growth potency)." (PMID 35956024, 2022). "PRL drives development of mammary cancers in mice with germline ablation of Stat1 secondary to somatic truncating mutations in Prlr, resulting in an alternatively spliced protein resembling the human “intermediate” isoform (see Sections 3.1, 3.4.2)." (PMID 35784527, 2022). "This review also stresses the importance of signal transduction pathways (PI3K/AKT, RAF/MEK/ERK, FAK, and SFK) activated by PRL/PRLR in breast cancer." (PMID 36187116, 2022). "Prolactin (PRL)-increasing and PRL-sparing antipsychotics posed a similar risk of breast cancer (OR, 1.13; 95% CI, approximately 0.97–1.31)." (PMID 36591471, 2022). "H53 also inhibited the PRL-induced phosphorylation of both STAT3 and STAT5, and AKT at a dose of 5-10 g/ml in T47D and MCF7 breast cancer cell lines, and further attenuated PRL-induced proliferation." (PMID 36714582, 2022). "Here, we will highlight recent discoveries supporting an anti-tumorigenic role for PRL in breast cancer as a “pro/forward-differentiation” pathway restricting plasticity, stemness and tumorigenesis." (PMID 36157462, 2022). "In summary, PRL imparts significant anti-tumorigenic effect in breast cancer through differentiation and terminal maturation." (PMID 36157462, 2022). "Although few actions of PRL at stromal targets have been addressed experimentally in the context of breast cancer, data from physiologic and other pathologic states suggest the need for additional study." (PMID 35784527, 2022). "Most human breast cancers arise from the epithelial cells, and prolactin stimulates mammary epithelial cells to synthesize milk components." (PMID 36313069, 2022). "Together, these approaches will unravel the complex actions of PRL, permitting a new understanding of the role of this third hormone in breast cancer, with implications for prevention and treatment." (PMID 35784527, 2022). "Further, as discussed in Section 2.2.3, many other stromal cell types which sculpt the tumor microenvironment are potential PRL targets, motivating additional study in the context of breast cancers." (PMID 35784527, 2022). "The contradictoryrelationship between prolactin and breast cancer, for example, deservesconsideration in case of a future proposal for prophylactic use of the hormone.It is worth remembering what happened with the ovarian steroid." (PMID 35857996, 2022). "In breast cancer xenograft models, PRL was found to induce tumor growth of T47D and MCF-7 tumors, while G129R-hPRL inhibited growth." (PMID 36714582, 2022). "In an experimental rat model of hormonally-responsive ER+ mammary cancer, concomitant inhibition of PRL and aromatase cooperatively reduced tumor growth." (PMID 35784527, 2022). "Additional studies with more specific reagents are needed to resolve the roles of the STAT5 isoforms in PRL actions in breast cancer." (PMID 35784527, 2022). "Of particular interest for premenopausal breast cancer, PRL-activated STAT5 suppressed a progestin-induced progenitor population in T47D breast cancer cells." (PMID 35784527, 2022). "We further investigated the effects of PRL-increasing and PRL-sparing antipsychotics on breast cancer prevalence." (PMID 36591471, 2022). "Verification was performed in a third assay of T47D breast cancer cells stably transfected with luciferase reporter driven by a PRL-responsive promoter." (PMID 36714582, 2022). "Altogether, there is now a large body of evidence implicating PRL/PRLR pathway as a clinically relevant anti-tumorigenic pathway in breast cancer." (PMID 36157462, 2022). "Studies in BC-derived cell lines demonstrated the mitogenic action of PRL, and activation of PRL-R has been shown to be sufficient and required for the induction of mammary carcinoma in mice." (PMID 35207645, 2022).